PRAME (PRAME nuclear receptor transcriptional regulator)
Diseases named in the same sentence as PRAME in open-access papers (continued):
Sharing a sentence is not in itself a finding about the gene and the disease.
neuroblastoma (13 papers, 2006 to 2025). Neuroblastoma (NB) is the most common solid, extracranial childhood tumor. "The expression of PRAME is associated with poor prognosis in neuroblastoma: high PRAME expression is associated with more advanced tumour stage, higher ages of patients at diagnosis, and poor clinical outcome." (PMID 18648365, 2008). "The rate of PRAME expression was reported to be up to 93% in primary neuroblastoma samples and 100% in patients with advanced disease." (PMID 40868240, 2025). "PRAME expression is notably prevalent in neuroblastoma, particularly in the disease’s advanced stages." (PMID 40868240, 2025). "While this antigen is yet to be clinically evaluated, pre-clinical analysis has identified PRAME expression in 93 % of primary and 100 % of advanced neuroblastoma patient tumour samples." (PMID 39489087, 2024). "The functional consequences of this drug‐mediated induction of MHC‐I were tested in a co‐culture system consisting of neuroblastoma cell lines and T‐cells directed against the neuroblastoma‐specific Preferentially Expressed Antigen in Melanoma (PRAME) antigen." (PMID 36840349, 2023). "TAA encoded by cancer/germline genes, including PRAME, NY-ESO1, MAGE and GAGE, can be expressed by neuroblastoma tumors." (PMID 26452036, 2015). "We first confirmed PRAME mRNA expression in neuroblastoma cell lines, using quantitative real-time PCR." (PMID 26452036, 2015). "We showed for neuroblastoma cells which are modulated by interaction with active NK cells, that the presence of endogenous levels of PRAME is sufficient for productive peptide presentation to T-cells." (PMID 26452036, 2015). "Whereas the expression of most cancer/germline antigens in neuroblastoma was shown to be very heterogeneous, PRAME expression was observed in 94% of stage 4 neuroblastoma samples." (PMID 26452036, 2015). "We show that oncoprotein PRAME serves as an immunodominant antigen for neuroblastoma as NK-modulated neuroblastoma cells are recognized by PRAMESLLQHLIGL/A2-specific CTL clones." (PMID 26452036, 2015). "Furthermore, elevated PRAME levels have been linked to poorer overall survival (OS) and event-free survival (EFS) in neuroblastoma patients." (PMID 40868240, 2025). "High protein expression of PRAME in neuroblastoma and osteosarcoma have previously been reported." (PMID 34818552, 2021). "Furthermore, we show for the first time that PRAME serves as an immunogenic tumor antigen for neuroblastoma as NK-modulated neuroblastoma cells present PRAME-derived peptide/MHC I complexes and are now recognized by PRAME-specific CTLs." (PMID 26452036, 2015). "PRAME is located at chromosome 22q11.22, with no known aberrations in neuroblastoma and, therefore, a potentially significant site to target with immunotherapeutics." (PMID 39489087, 2024). "For some genes only circumstantial evidence for a role in neuroblastoma is present (WSB1, CDC42, PLAGL1, PRAME and TGFBR3); that we identified these genes in the present study warrants further investigations into their possible role in neuroblastoma development." (PMID 16989664, 2006). "Co-culture of activated NK cells with neuroblastoma cell lines demonstrated that the tumor cells could upregulate the expression of MHC class I molecules through NK contact-dependent production of IFN-γ, resulting in increased PRAME-specific T cell killing of the tumor cells." (PMID 31311081, 2019).
seminoma (12 papers, 2015 to 2025). A radiosensitive malignant germ cell tumor found in the testis (especially undescended), and extragonadal sites (anterior mediastinum and pineal gland). "According to earlier publications, each histologic subtype has different gene signatures identified by transcriptional profiling: seminomas have overexpressed spermatogenesis-associated genes like PRAME, MAGEA4 and SPAG1 while NSGCTs have overexpressed regulatory genes such as DNMT3B and SOX2." (PMID 40011822, 2025). "Another study in seminomas indicates that the overexpression of PRAME and its interaction with Lin28A support pluripotency networks and expression of reprogramming markers, such as DPPA3, Nanog, Oct3/4, ZSCAN10, and PRDM14." (PMID 40961095, 2025). "A recent study reported differential expression of PRAME in seminomas and seminoma components of mixed tumors." (PMID 38541782, 2024). "This disparity is believed to result from PRAME involvement in the “reprogramming” of seminoma cells towards the embryonal carcinoma phenotype." (PMID 38541782, 2024). "So, PRAME expression correlates to SOX17 expression and can be associated with a PGCs / seminoma cell fate." (PMID 28244655, 2017). "Under in vitro differentiating conditons both, the parental and SOX2-deficient TCam-2 cells downregulated pluripotency/seminoma markers OCT3/4, TFAP2C, PRDM14 and PRAME, while SOX2 and DNMT3B expression remained low." (PMID 27283990, 2016). "Other neoplasms such as seminomas and carcinomas of various origins including endometrial, serous ovarian, mammary ductal, lung, and renal showed an intermediate proportion of cases and variable extent of tumor cells positive for PRAME protein expression." (PMID 39379758, 2024). "Thus, SOX17 / PRAME is critically important for maintenance of an undifferentiated dormant pluripotent seminoma fate." (PMID 28244655, 2017). "Additionally, global 5mC levels remained unaffected and expression of seminoma-associated genes SOX17, PRAME, TFAP2C, PRDM1 and cKIT was maintained." (PMID 27283990, 2016). "PRAME is downstream of SOX17 and LIN28 for regulating pluripotency and controlling germ cell differentiation in seminoma cells." (PMID 38132219, 2023). "TCam-2 cells express typical primordial germ cell and GCNIS marker genes (SOX17, PRAME, cKIT, TFAP2C, PRDM1/BLIMP1) and show a typical GCNIS/seminoma morphology (big roundish cells with a big nucleus and clear cytoplasm)." (PMID 31130628, 2019). "Most importantly, the majority of TCam-2-ΔSOX2 cells maintains a seminoma-like cell fate for at least 6 weeks in vivo, indicated by a typical seminoma-like morphology and expression of seminoma markers SOX17, PRAME, TFAP2C and PRDM1 (nuclear)." (PMID 27283990, 2016). "In TCam-2-ΔSOX2 clones, expression of seminoma markers SOX17, PRAME, TFAP2C, LIN28 and PRDM1 was slightly downregulated or remained unchanged compared to the TCam-2 in vitro cells." (PMID 27283990, 2016). "Among them, GDF3, NODAL, LEFTY1 /2, GAL, DPPA3, SOX2, DNMT3B /L, DPPA5, BCAT1, FGF2, PRDM14, ZIC3 and FZD7, while seminoma markers SOX17, cKIT and PRAME were downregulated." (PMID 26226633, 2015). "Additionally, strong and comparable expression of the seminoma and pluripotency markers OCT3/4, NANOG, LIN28, SOX17, PRAME, PRDM1/BLIMP1 and TFAP2C was found in TCam-2, TCam-2-ΔSOX2 and TCam-2-ΔSOX2/FOXA2 cells." (PMID 31130628, 2019). "Additionally, many pluripotency and EC associated genes, like SOX2, ZIC3, ZFP42, LIN28, SALL4 and PRDM14 were upregulated without correlating to changes in their 5mC status, while seminoma markers SOX17, cKIT, PRDM1 and PRAME were downregulated." (PMID 27283990, 2016). "Expression of typical seminoma markers (PRDM1/BLIMP1, SOX17, PRAME, TFAP2C) was also detectable in TCam-2-ΔSOX2/FOXA2 tumor tissues, in contrast to EC reprogramming factors (GDF3, DPPA3, DNMT3B, GAL), which could only be detected in 2102EP in vivo or reprogrammed TCam-2 cells." (PMID 31130628, 2019).
seminoma (continued). "Furthermore, additional EC and pluripotency genes were upregulated (SOX2, LEFTY1 /2, DNMT3L, SALL4, DPPA5, BCAT1, FZD7, LIN28, ZIC3), while seminoma-associated genes where downregulated (SOX17, TFAP2C, cKIT, PRAME), without changing 5mC-levels." (PMID 26226633, 2015). "We stratified the TCGA dataset of 156 samples into a seminoma expression signature (SOX17, PRAME, PRDM1 positive; SOX2, DNMT3B, GAL negative) and an EC expression signature (SOX2, DNMT3B, GAL positive; SOX17, PRAME, PRDM1 negative)." (PMID 32418994, 2020).
synovial sarcoma (12 papers, 2008 to 2024). "Another melanoma-associated antigen, PRAME (Preferentially expressed Antigen in Melanoma), has been detected in medulloblastoma and synovial sarcoma, promising a potential therapeutic target." (PMID 36077730, 2022). "In synovial sarcomas, a positive association between expression of PRAME and DNMT3A was identified." (PMID 38541782, 2024). "However, we also discovered that PRAME expression negatively correlates with genes involved in antigen presentation, and in synovial sarcoma MHC class I antigen presentation deficiencies are also present, potentially limiting the efficacy of immunotherapies of this malignancy." (PMID 28630682, 2017). "Tumors from three different lineages (sinonasal melanoma, testicular seminoma, and synovial sarcoma), identified to have common yet variable PRAME immunoreactivity, were studied." (PMID 38541782, 2024). "Variable degrees of PRAME staining have been sporadically observed in other malignant tumors, including most synovial sarcomas, myxoid liposarcomas, and malignant peripheral nerve sheath tumors (MPNST)." (PMID 39379758, 2024). "For TGAs, we identified 43 genes, including those that are currently under clinical investigation as ACT targets such as NY-ESO-1 (CTAG1A) in synovial sarcoma, and PRAME in a number of histologic types." (PMID 34818552, 2021). "The activity of MAGEA1 (25% 1/4), NYESO1 (50% 2/4), and PRAME (75% 3/4) genes were also found in the cells of four samples of synovial sarcomas." (PMID 32042403, 2020). "Our analysis of PRAME expression associations with subtypes and clinical variables revealed that PRAME is overexpressed in synovial sarcoma and in multifocal leiomyosarcoma." (PMID 28630682, 2017). "PRAME expression was detected in all synovial sarcoma samples." (PMID 39451213, 2024). "PRAME co-overexpression with NY-ESO-1 in synovial sarcoma suggests that this antigen may also be targeted efficiently by these immunotherapy approaches." (PMID 28630682, 2017). "We found that uterine carcinosarcoma highly overexpresses the PRAME antigen, and synovial sarcomas and multifocal leiomyosarcomas also show high expressions suggesting that PRAME may be an effective target of immunotherapies of these tumors." (PMID 28630682, 2017). "Furthermore, we found that synovial sarcoma, which overexpresses PRAME, showed a significantly lower B2M and CD8A expressions compared to other subtypes." (PMID 28630682, 2017). "Importantly, a few of the LMS, UPS/MFS, DDLPS, and MPNST tumors also showed high PRAME expressions, suggesting that in addition to synovial sarcomas, these subtypes may also be considered for immunotherapies targeting PRAME." (PMID 28630682, 2017). "Co-expression of PRAME and NY-ESO-1 has been shown to correlate with high-grade histologic features and a worse overall survival in patients with myxoid liposarcomas and synovial sarcomas." (PMID 28630682, 2017). "Also, PRAME was expressed in 100% of the non-myxoid liposarcomas and synovial sarcomas, but none of the AF or MFH-B samples." (PMID 18460215, 2008).
osteosarcoma (10 papers, 2012 to 2025). A usually aggressive malignant bone-forming mesenchymal neoplasm, predominantly affecting adolescents and young adults. "Positive rates of MAGE‐A1, MAGE‐A4, NY‐ESO‐1, and PRAME in osteosarcoma, liposarcoma, leiomyosarcoma, UPS, and chondrosarcoma in references and our data." (PMID 40152485, 2025). "PRAME knockdown significantly suppressed the proliferation, colony formation, and G1 cell cycle arrest in osteosarcoma cells." (PMID 32042403, 2020). "High protein expression levels of PRAME have been shown to correlate with a worse overall survival in osteosarcoma, and the expression of PRAME was more common in metastases compared to primary tumors." (PMID 28630682, 2017). "PRAME promotes the proliferation of osteosarcoma cells, while in Chronic myelogenous leukemia, in the presence of RA and PcG proteins, including EZH2, it binds to retinoic acid receptor (RAR) to block Caspase 3, TRAIL, and P21 expression, leading to proliferation and apoptosis arrest." (PMID 40961095, 2025). "Other studies reported MAGEA and PRAME expression in osteosarcoma." (PMID 32042403, 2020). "PRAME siRNA knockdown significantly suppressed proliferation, induced cell cycle stop in the G1 phase, reduced the efficiency of colony formation of cultured cells by osteosarcoma." (PMID 32042403, 2020). "PRAME was also over-expressed in 12/29 osteosarcoma clinical samples based on identical types of microarray data (no methylation data was available), and has also recently been shown by others to be over-expressed in osteosarcomas." (PMID 23144859, 2012). "Osteosarcoma, synovial sarcoma, and myxoid/round cell liposarcoma show very high expression of MAGE and PRAME." (PMID 40152485, 2025). "Osteosarcoma was characterized by the presence of GAGE (40% 2/5), MAGEA1 (60% 3/5), PRAME (40% 2/5), NY-ESO1 (40% 2/5), PASD1 (60% 3/5), SLLP1 (60% 3/5), SSX1 (80% 4/5)." (PMID 32042403, 2020).
liposarcoma (8 papers, 2008 to 2025). A usually painless malignant tumor that arises from adipose tissue. "Interestingly, PRAME expression in dedifferentiated liposarcoma and leiomyosarcoma tumours was found to be associated with reduced expression of antigen presentation molecules, a common mechanism of immune escape." (PMID 34612587, 2021). "PD-L1 and PRAME expression also negatively correlated in dedifferentiated liposarcoma." (PMID 28630682, 2017). "Next, we performed in silico gene expression analysis of PRAME, EZH2, and the RAR genes in synovial, leiomyosarcoma, rhabdomyosarcoma, and liposarcoma STS cell lines." (PMID 39550391, 2024). "The current results confirmed our earlier report of over-expression of PRAME, CTAG1 and CTAG2 in liposarcomas using the U_95 array with the newer U_133 array, and also demonstrated that the expression of these potential targets of immunotherapy is heterogeneous among STS." (PMID 18460215, 2008).
myeloma (8 papers, 2020 to 2024). "As PRAME is expressed not only in solid tumors but also in the cells of leukemia and myeloma patients, this suggests a broad potential application." (PMID 39204391, 2024). "In vivo killing potential of the PRAME TCRs was tested in an established model for multiple myeloma (MM), since PRAME is also expressed in MM." (PMID 37026005, 2023). "PRAME gene as a class of tumor antigen, having a varied expression in a different malignancy like chronic lymphoproliferative disorders, multiple myeloma, acute, and chronic leukemia’s." (PMID 35788450, 2022). "PRAME expression has been described in a variety of hematologic malignancies, including both acute and chronic myeloid and lymphocytic leukemias, hairy cell leukemia, Hodgkin’s lymphoma, diffuse large B-cell lymphoma, mantle cell lymphoma, and multiple myeloma." (PMID 35076507, 2021). "As reported in international studies, the PRAME gene is also expressed in AML, ALL, multiple myeloma, and chronic myeloid leukemia." (PMID 35788450, 2022). "PRAME, another CTA located in the 22nd chromosome, was also strongly expressed in all myeloma cell lines, which is consistent with reports that gene expression levels are lower in X chromosomal genes than in autosomal genes." (PMID 33023190, 2020).
triple-negative breast carcinoma (8 papers, 2019 to 2025). An invasive breast carcinoma which is negative for expression of estrogen receptor (ER), progesterone receptor (PR), and human epidermal growth factor receptor 2 (HER2). "Similar to the CTA member NY-ESO-1, PRAME was identified as an immunogenic tumor-associated antigen in melanoma, and since its discovery its expression has been demonstrated in a variety of solid and hematological malignancies including triple negative breast cancer." (PMID 30602372, 2019). "PRAME plays a tumor-promoting role in triple-negative breast cancer by increasing cancer cell motility through EMT-gene reprogramming." (PMID 35186034, 2022). "In order to study the role of PRAME in triple negative breast cancer, PRAME expression was manipulated by transient silencing in BT549 cells and stable overexpression in MDA-MB-468 cells." (PMID 30602372, 2019). "More specifically, we explored the molecular function of PRAME in cell migration and invasion of triple negative breast cancer cells." (PMID 30602372, 2019). "PRAME has a tumor-promoting role in triple-negative breast cancer, increasing cancer cell motility through the epithelial-to-mesenchymal transition (EMT) gene reprogramming." (PMID 31850079, 2019). "Using several approaches, we show here that PRAME expression increases the cell motility of triple negative breast cancer cells." (PMID 30602372, 2019). "This is the first in vitro study to investigate the role of PRAME in metastasis of triple negative breast cancer by manipulating its expression using 2 different approaches, either by silencing or overexpressing PRAME." (PMID 30602372, 2019). "Our findings indicate that PRAME plays a tumor-promoting role in triple negative breast cancer by increasing cancer cell motility through EMT-gene reprogramming." (PMID 30602372, 2019). "Given the inherent mesenchymal phenotype of triple negative breast cancer cells, we determined the expression of the mesenchymal marker vimentin and the epithelial marker E-cadherin in relation to PRAME expression." (PMID 30602372, 2019). "Furthermore, the upregulation of PRAME features cell stemness, invasion, and metastasis in triple-negative breast cancer by promoting the epithelial-to-mesenchymal transition (EMT) through the activation of ZEB1 and downregulation of BMP7 and TSPAN13 genes)." (PMID 33804612, 2021). "This supports our hypothesis that PRAME, and its network, might play an important role in the acquisition of cellular traits that confer the aggressive behavior of triple negative breast cancer." (PMID 30602372, 2019). "Therefore, PRAME could serve as a prognostic biomarker and/or therapeutic target in triple-negative breast cancer." (PMID 31850079, 2019). "We demonstrate that PRAME facilitates the transition to a mesenchymal phenotype through reprogramming of several EMT-genes, resulting in enhanced migration and invasion of triple negative breast cancer cells." (PMID 30602372, 2019).